OR1J2 (olfactory receptor family 1 subfamily J member 2)
Description:
Odorant receptor.
Synonyms: OR1J3; OR1J5; OST044; HG152; HSA5; OR9-19
Tractability: Small molecule: it belongs to a druggable protein family. Antibody: UniProt places it where antibodies can reach, with medium confidence; UniProt predicts a signal peptide or a membrane-spanning region; its Gene Ontology location is reachable by antibodies, with medium confidence.
Gene: Protein-coding gene on chromosome 9 (122,510,802 to 122,511,743, forward strand). Ensembl gene ENSG00000197233.
Subcellular location: Cell membrane
Pathways (Reactome):
Sensory Perception: Expression and translocation of olfactory receptors
Gene Ontology:
Molecular function: olfactory receptor activity; G protein-coupled receptor activity
Biological process: signal transduction; detection of chemical stimulus involved in sensory perception of smell; G protein-coupled receptor signaling pathway
Cellular component: plasma membrane; membrane
Genetic constraint (gnomAD): Missense variants: 68 observed, 78.73 expected, observed/expected ratio (o/e) 0.86, 90% interval 0.71 to 1.06. Synonymous variants: 39 observed, 36.75 expected, observed/expected ratio (o/e) 1.06, 90% interval 0.82 to 1.39.
Homologues: Orthologues: chimpanzee OR1J2 (99% identical). Paralogues in human: OR1J4 (78% identical), OR1J1 (74% identical), OR1E1 (60% identical), OR1E2 (60% identical), OR1F1 (55% identical), OR7C1 (55% identical), OR1M1 (54% identical), OR7C2 (54% identical), OR1N1 (53% identical), OR1S1 (53% identical), OR7D2 (53% identical), OR1L8 (52% identical), and 116 more.
Diseases named in the same sentence as OR1J2 in open-access papers:
OR1J2 is named in the same sentence as 2 diseases in open-access papers, as found by Europe PMC text mining. Sharing a sentence is not in itself a finding about the gene and the disease. The quoted sentences say what the papers report.
tumor (1 paper, 2018). "Together with TMEM140, TEAD2, OR1J2, and GRIN2B, many other genes were commonly mutated across the tumor samples, however the recurrence always occurred when examining multiple metastatic samples of the same individual (T07–11 or T04–05 corresponding respectively to patients P06 and P04)." (PMID 29510530, 2018).
OR1J2 also shares sentences with these, for which no sentence is quoted: pancreatic cancer (3 papers).